FNDC4 (fibronectin type III domain containing 4)
Description:
[Soluble FNDC4]: Has anti-inflammatory properties. In the colon, acts on macrophages to down-regulate inflammation. May suppress osteoclastogenesis and mature osteoclast resorptive function. In white adipose tissue, decreases local inflammation, via interaction with GPR116. Also required for proper systemic glucose tolerance, specifically sensitizing white adipocytes to insulin and promoting glucose uptake. The insulin sensitizing function in adipose tissue is mediated by interaction with ADGRF5/GPR116 and activation of cAMP signaling.
Synonyms: FRCP1; FLJ22362
Tractability: Antibody: UniProt places it where antibodies can reach, with medium confidence; UniProt predicts a signal peptide or a membrane-spanning region; its Gene Ontology location is reachable by antibodies, with medium confidence.
Gene: Protein-coding gene on chromosome 2 (27,491,883 to 27,495,631, reverse strand). Ensembl gene ENSG00000115226.
Subcellular location: Membrane (Fibronectin type III domain-containing protein 4); Secreted (Soluble FNDC4)
Subcellular location (Human Protein Atlas): Nucleoplasm; Aggresome; Cytosol
Gene Ontology:
Biological process: response to transforming growth factor beta; negative regulation of inflammatory response
Cellular component: endoplasmic reticulum; extracellular region; plasma membrane; membrane
Genetic constraint (gnomAD): Loss-of-function variants: 11 observed, 26.16 expected, observed/expected ratio (o/e) 0.42, 90% interval 0.26 to 0.7. The upper end of that interval is the gene's LOEUF score, 0.7, which puts it in group 2 of 6, group 1 being the genes least tolerant of losing a copy. Missense variants: 250 observed, 320 expected, observed/expected ratio (o/e) 0.78, 90% interval 0.7 to 0.87. Synonymous variants: 136 observed, 126.37 expected, observed/expected ratio (o/e) 1.08, 90% interval 0.94 to 1.24.
Homologues: Orthologues: chimpanzee FNDC4 (99% identical), rat Fndc4 (95% identical), dog FNDC4 (94% identical), mouse Fndc4 (94% identical), guinea pig FNDC4 (94% identical), macaque FNDC4 (94% identical), pig FNDC4 (94% identical), rabbit FNDC4 (88% identical). Paralogues in human: FNDC5 (42% identical).
Diseases named in the same sentence as FNDC4 in open-access papers:
FNDC4 is named in the same sentence as 52 diseases in open-access papers, as found by Europe PMC text mining. Sharing a sentence is not in itself a finding about the gene and the disease. The quoted sentences say what the papers report.
inflammatory bowel disease (7 papers, 2016 to 2025). A spectrum of small and large bowel inflammatory diseases of unknown etiology. "Among these genes, previous studies had reported that FNDC4 (fibronectin type III domain containing 4), RNF186 (ring finger protein 186), and UBASH3A (ubiquitin associated and SH3 domain containing A) were associated with inflammatory bowel disease." (PMID 33043022, 2020). "Specifically, FNDC4 levels are increased locally at inflamed sites of the intestine of inflammatory bowel disease patients." (PMID 27066907, 2016). "Thus, we have characterized FNDC4 as a factor with direct therapeutic potential in inflammatory bowel disease and possibly other inflammatory diseases." (PMID 27066907, 2016). "FNDC4 was described as anti-inflammatory factor, upregulated in inflammatory bowel disease (IBD)." (PMID 31093274, 2019). "In addition, previous study has shown that FNDC4 and FNDC1, but not FNDC5, are significantly increased in human inflammatory bowel disease, and FNDC4 has been described as an anti-inflammatory factor." (PMID 39567831, 2025).
Obesity (7 papers, 2018 to 2026). Accumulation of substantial excess body fat. "There is a positive association between the expression of FNDC4 and obesity-associated inflammation." (PMID 36575472, 2022). "In conclusion, FNDC4 may offer a novel treatment approach for diabetes associated with obesity." (PMID 39325938, 2024). "Fibronectin Type III Domain Containing 4 (FNDC4), a protein released by adipocytes in obesity, has anti-inflammatory effects on macrophages." (PMID 39768436, 2024). "The potential beneficial effects of FNDC4 on COVID-19 outcomes include anti-obesity and anti-inflammatory activities, such as inhibiting M1 polarization of macrophages and pro-inflammatory cytokine production in AT." (PMID 39325938, 2024). "At present, studies have found that FNDC4 directly participates in lipid metabolism of adipocytes, thereby affecting the pathological and physiological states related to obesity." (PMID 39325938, 2024). "The major mediator of beiging in visceral fat released by adipocytes in obesity is fibronectin type III domain-containing protein 4 (FNDC4) which probably targets the receptor GRP116." (PMID 36575472, 2022). "Overall, research has shown that FNDC4 levels are closely related to obesity related factors such as body fat, weight, and systemic inflammatory status, and may become a new therapeutic target for improving obesity related metabolic disorders." (PMID 39325938, 2024). "Comparing the body weight of AAV-injected Sim1-cre mice versus AAV-injected wild-type littermates, we found that overexpression of Snca and Igsf8 caused an exacerbation of HFD-induced obesity, whereas overexpression of Spata2, Pole4, Fndc4, Smim12, or Arrb1 had no impact on body weight." (PMID 36175420, 2022).
colitis (5 papers, 2016 to 2024). Inflammation of the colon. "FNDC4 is an anti-inflammatory factor that alters the activation state of macrophages; it is used to treat colitis in mice." (PMID 32881638, 2020). "A recent study has attributed the therapeutic effect of FNDC4 in colitis to its inhibitory effect on macrophages." (PMID 32881638, 2020). "FNDC4 acts as an anti-inflammatory factor on macrophages and improves mouse model of induced colitis." (PMID 29977911, 2018). "FNDC4 supplementation reduced disease severity in a mouse model for colitis, indicating therapeutic potential." (PMID 27066907, 2016). "FNDC4 supplementation in vivo attenuated DSS-induced colitis, indicating that FNDC4 has therapeutic potential." (PMID 27066907, 2016). "Induction of colitis resulted in increased disease severity in the Fndc4 KO mice, as shown by increased disease severity index, reduced colon length, increased body weight loss, increased histopathology scores and increased proinflammatory gene expression." (PMID 27066907, 2016). "FNDC4 treatment of mice with DSS-induced colitis resulted in reduced inflammation and clinical improvement, suggesting therapeutic potential." (PMID 27066907, 2016). "Mice were injected with hFc-FNDC4 or hFc control followed by induction of colitis by addition of DSS to the drinking water for 5 days." (PMID 27066907, 2016). "It is thus likely that therapeutic delivery of FNDC4 partially blocks phagocytosis also in vivo, which would be consistent with previous reports where blockage of phagocytosis function attenuated colitis in mice." (PMID 27066907, 2016). "Administering FNDC4 to mice with DSS-induced colitis resulted in downregulation of expression of the proinflammatory chemokines Cxcl9 and Cxcl10 (Ip10), consistent with the in vitro data in macrophages." (PMID 27066907, 2016). "In the mice model of induced colitis, FNDC4 treatment could markedly reduce inflammation and ameliorate disease severity, suggesting the potential therapeutic effect." (PMID 29977911, 2018). "Furthermore, histopathology scores for colitis severity were significantly lower in the hFc-FNDC4-treated mice, supporting the beneficial effects of hFc-FNDC4 supplementation in colitis." (PMID 27066907, 2016). "Importantly, Fndc4 KO mice showed increased colitis severity, suggestive of a requirement for FNDC4 to dampen the immunological response in colitis." (PMID 27066907, 2016). "In summary, therapeutic delivery of FNDC4 reduced the disease severity of colitis in mice." (PMID 27066907, 2016). "Interestingly, administration of recombinant FNDC4 in the mouse model of induced colitis markedly reduces disease severity compared with mice injected with a control protein." (PMID 27066907, 2016). "To evaluate whether FNDC4 is not only sufficient, but also required for immune dampening in colitis, we investigated DSS-induced colitis development and severity in Fndc4 KO mice." (PMID 27066907, 2016). "Subsequently, we sought to elucidate the cell type targeted by FNDC4 in colitis." (PMID 27066907, 2016). "Moreover, FNDC4 reportedly plays a role in promoting fat browning, similar to FNDC5, and is an anti-inflammatory factor capable of improving colitis symptoms by specifically binding to macrophages." (PMID 36056336, 2022). "Since FNDC4 mainly targets macrophages, STAT3 activation may have contributed to the attenuation of colitis symptoms in the FNDC4-treated mice." (PMID 27066907, 2016).
Insulin resistance (5 papers, 2021 to 2024). Increased resistance towards insulin, that is, diminished effectiveness of insulin in reducing blood glucose levels. "Furthermore, FNDC4 suppresses ER stress in adipocytes, which reduces insulin resistance caused by hyperlipidemia." (PMID 39001944, 2024). "Previous studies have shown that FNDC4 participates in the body's glucose metabolism by improving insulin resistance." (PMID 39325938, 2024). "We provide evidence that FNDC4 acts as an endocrine factor, which controls systemic glucose tolerance and responds to insulin-sensitizing treatments such as diet, exercise, or BS in conjunction with the reversal of T2D and improvements in insulin resistance in mice and humans." (PMID 34016966, 2021). "Their results show that FNDC4 can improve insulin resistance by inhibiting inflammation and ER stress through the AMPK/HO-1 mediated pathway, suggesting that FNDC4 may be a new therapeutic agent for insulin resistance and T2D." (PMID 39325938, 2024).
liver cancer (5 papers, 2021 to 2024). An epithelial or non-epithelial malignant neoplasm that arises from the liver. "In addition, enrichment analysis from TCGA liver cancer database showed that the expression of FNDC4 was associated with cell migration ability." (PMID 38021165, 2023). "The same study used HepG2 as a model cell line to display that upregulation of FNDC4 promotes liver cancer cell migration and invasion in vitro via the PI3K/Akt signaling pathway." (PMID 39596661, 2024). "At the same time, through clinical feature analysis of 205 HCC patients and survival analysis based on FNDC4, it was concluded that high expression of FNDC4 is positively correlated with microvascular invasion and low differentiation of liver cancer cells." (PMID 39325938, 2024). "Through bioinformatics analysis, we found that compared with that in normal liver tissue, the expression level of FNDC4 in liver cancer tissues was significantly downregulated." (PMID 38021165, 2023). "In our study, we found that FNDC4 was highly expressed in normal liver tissues but abnormally expressed at low levels in liver cancer tissues." (PMID 38021165, 2023). "Our results showed that FNDC4 had certain clinical research value and was expected to become a potential target or biomarker for the diagnosis and treatment of liver cancer." (PMID 38021165, 2023). "Because of the decreased expression of FNDC4 in liver cancer tissues, we further constructed an overexpression model of FNDC4 in HepG2 cells." (PMID 38021165, 2023). "Our study suggests that FNDC4 is a potential target or biomarker for the future diagnosis and treatment of liver cancer, providing theoretical support for subsequent relevant research, but still more data are needed." (PMID 38021165, 2023). "To evaluate the effects of FNDC4 on liver cancer cell migration and invasion, we conducted in vitro cell assays." (PMID 34418326, 2021). "To further research the correlation between FNDC4 and liver hepatocellular carcinoma, we compared the expression level of FNDC4 in liver cancer tissues with that in normal liver tissues based on patient sex, weight, age, tumor grade, and individual cancer stage." (PMID 38021165, 2023). "Therefore, we conducted a scratch experiment to verify the changes in the migration ability of liver cancer cells after high expression of FNDC4 and found that the wound closure rate was reduced in the overexpression model." (PMID 38021165, 2023). "We speculated that the stimulating effect of FNDC4 on proinflammatory cytokines and immune cells in the late liver cancer stage may aggravate the process of liver fibrosis, just as TGF-β promotes the differentiation of mesenchymal cells into hepatic stellate cells and myofibroblasts." (PMID 38021165, 2023). "Specifically, the expression level of FNDC4 in invasive ductal carcinoma of breast (IDC), lobular and ductal mixed breast cancer, liver cancer (HCC), serous adenocarcinoma of ovary, esophageal cancer, prostate cancer, sarcoma, etc. is low." (PMID 39325938, 2024). "In summary, both FNDC4 overexpression by lentiviral transfection and endogenous FNDC4 induction by TGF‐β1 promote the invasion and metastasis of liver cancer." (PMID 34418326, 2021). "Additionally, compared to normal liver tissues, FNDC3A and FNDC4 showed lower expression, while FNDC3B and FNDC8 displayed higher expression in liver cancer." (PMID 36626432, 2022).
glioblastoma (4 papers, 2022 to 2024). The most malignant astrocytic tumor (WHO grade IV). "FNDC4 expression is elevated in glioblastoma, closely associated with poor prognosis, and promoted the proliferation of glioblastoma cells, affected the S phase of tumor cells while inhibiting macrophage polarization." (PMID 36056336, 2022). "We identified that significantly higher FNDC4 expression in glioblastoma tissue relative to normal brain tissue was associated with worse prognosis." (PMID 36056336, 2022). "Similarly, FNDC4 is associated with unfavorable outcomes in glioblastoma, enhancing cell proliferation and influencing the S phase of tumor cells." (PMID 39768218, 2024). "However, in the present study, we found that FNDC4 promoted only the proliferation of glioblastoma cells, the potential mechanism associated with which may be related to the observed inhibition of M1 macrophage polarization by exocrine FNDC4." (PMID 36056336, 2022). "In this study, we investigated the role(s) of FNDC4 in glioblastoma by combining bioinformatics analysis, functional experiments, and correlation analyses." (PMID 36056336, 2022). "Analyses revealed significant differences in FNDC4 expression between normal brain tissue and that affected by glioblastoma (P = 1.67e-13); these findings were confirmed using data from the CGGA database (P = 4.71e-10)." (PMID 36056336, 2022). "We found that the CD80:CD206 ratio decreased significantly when co-culturing FNDC4-overexpressing glioblastoma cells with M1 macrophages." (PMID 36056336, 2022). "The results showed that FNDC4 promoted tumor proliferation in glioblastoma, affected the S phase of tumor cells and inhibited the polarization of M0 macrophages to the M1 phenotype." (PMID 36056336, 2022). "This study explored the potential mechanism of FNDC4 in glioblastoma through bioinformatics analysis and cell-based experiments." (PMID 36056336, 2022). "In both databases, high and low expression of FNDC4 was significantly correlated with glioblastoma patient prognosis (P = 0.01 and P = 0.015, respectively)." (PMID 36056336, 2022). "We found that FNDC4 expression in glioblastoma positively correlated (r2 > 0.4) with scores determined for immune cell infiltration (P = 1.4e-08)." (PMID 36056336, 2022). "We extracted FNDC4-expression for 212 normal specimens from the GTEx database and combined them with data from 167 glioblastoma patients from the TCGA database." (PMID 36056336, 2022). "We found that FNDC4 expression in tumor tissues was significantly higher than that in normal brain tissues, and that glioblastoma patients with elevated FNDC4 expression showed poor prognosis." (PMID 36056336, 2022). "This represents the first study to explore the potential mechanism and prognostic effect of FNDC4 in glioblastoma." (PMID 36056336, 2022). "This indicates that FNDC4 can guide the evaluation of the prognosis of glioblastoma." (PMID 39325938, 2024). "Furthermore, exogenous FNDC4 inhibited the M1 polarization of M0 macrophages without affecting M2 polarization; this was also observed in glioblastoma cells overexpressing FNDC4." (PMID 36056336, 2022). "Additionally, we overexpressed FNDC4 in glioblastoma cell lines U87 and U251 by lentiviral transfection and detected changes in proliferation, cell cycle progression, and apoptosis." (PMID 36056336, 2022). "We speculated that in glioblastoma, exocrine FNDC4 plays a vital role in the TIM by suppressing M0 macrophage polarization to M1, thereby inhibiting their antitumor functions and leading to tumor cell proliferation, increased tumor malignancy, and subsequent poor prognosis." (PMID 36056336, 2022). "Despite the FNDC family showing important regulatory roles in tumors, the role of FNDC4 has not been evaluated in glioblastoma." (PMID 36056336, 2022). "Additionally, flow cytometry results showed that FNDC4 overexpression did not affect glioblastoma cell apoptosis, but affected the S phase of tumor cells." (PMID 36056336, 2022).
hepatocellular carcinoma (4 papers, 2021 to 2024). A malignant tumor that arises from hepatocytes. "Elevated FNDC4 expression is linked to poor survival in hepatocellular carcinoma, where it promotes migration and invasion via the PI3K/Akt signaling pathway." (PMID 39768218, 2024). "We found that the transcription level of FNDC4 was significantly downregulated in hepatocellular carcinoma versus normal tissue." (PMID 38021165, 2023). "We found that FNDC4 expression was correlated with several tumor-infiltrating lymphocytes (TILs) in hepatoma patients, including monocytes (Spearman: r=0.377, p=5.79e-14) and Th17 cells (Spearman: r=0.32, p=3.02e-10)." (PMID 38021165, 2023). "In The Human Protein Atlas Database, the immunohistochemical pathological sections of FNDC4 in hepatocellular carcinoma also showed that, compared with normal liver tissue, FNDC4 was expressed at a low protein level in cancer tissues." (PMID 38021165, 2023). "Collectively, our results suggested that FNDC4 had a certain correlation with the occurrence of hepatocellular carcinoma." (PMID 38021165, 2023). "To investigate the role of FNDC4, especially in hepatocellular carcinoma, we first analyzed its transcriptional levels in normal tissues of different organs by using The Human Protein Atlas Database." (PMID 38021165, 2023). "We further investigated whether FNDC4 was a significant factor related to immune infiltration in hepatoma by using the TISIDB and TIMER databases." (PMID 38021165, 2023). "The expression of FNDC4 in hepatocellular carcinoma was significantly decreased." (PMID 38021165, 2023). "This further confirms the hypothesis that FNDC4 acts as a tumor suppressor gene in hepatocellular carcinoma." (PMID 38021165, 2023). "Therefore, we speculated that FNDC4 might play an inhibitory role in hepatocellular carcinoma by affecting the expression activity of some inflammatory cytokines, such as CD40, TNFSF14 or CXCL2." (PMID 38021165, 2023). "FNDC4 may act as a tumor suppressor gene in hepatocellular carcinoma." (PMID 38021165, 2023). "Regarding HCC survival, we examined the influence of FNDC4 on overall survival (OS), progression-free survival (PFS), relapse-free survival (RFS) and disease-specific survival (DSS) for the prognostic analyses of hepatocellular carcinoma using the Kaplan-Meier Plotter database." (PMID 38021165, 2023).
colorectal cancer (3 papers, 2019 to 2024). A primary or metastatic malignant neoplasm that affects the colon or rectum. "We here aim to comprehensively analyze the mRNA expression of FNDC1, FNDC3A, FNDC3B, FNDC4, FNDC5, and GPR116 in nonaffected and affected mucosal samples of patients with IBD or colorectal cancer (CRC)." (PMID 31093274, 2019).